FTO (FTO alpha-ketoglutarate dependent dioxygenase)
Diseases named in the same sentence as FTO in open-access papers (continued):
Sharing a sentence is not in itself a finding about the gene and the disease.
Obesity (continued). "Although the effect of the fat mass and obesity-associated (FTO) gene on adiposity is well established, there is a lack of evidence whether physical activity (PA) modifies the effect of FTO variants on obesity in Latino populations." (PMID 26908368, 2016). "Previous genome-wide association studies indicated the FTO region harbors the strongest genetic association with obesity, while no mechanistic association could be drawn." (PMID 26880991, 2016). "Further understanding of how FTO gene influences obesity and T2D through dietary and exercise interventions is warranted to advance the development of behavioral intervention and personalised lifestyle strategies, which could reduce the risk of metabolic diseases in this Asian Indian population." (PMID 27274759, 2016). "Since then, the genetic association of variant rs9939609 with obesity and T2D has been demonstrated in a Korean population based on GWAS results, and other studies have confirmed that the association of FTO variants with obesity or T2D is not dependent on ethnic background." (PMID 27249024, 2016). "Also, our data strongly support the hypothesis that sex plays an important role in the relationship between FTO SNPs and the development of obesity." (PMID 26726774, 2016). "However, we found replicable examples of non-additive effects at FTO on BMI and obesity, and at CDKAL1 on type 2 diabetes risk." (PMID 26961502, 2016). "However, no direct connection between obesity associated variants and FTO expression and function has been made." (PMID 26907388, 2016). "In conclusion, this study provides evidence for changes in phospholipid and amino acid metabolism that may be linked to obesity and T2D in FTO risk allele carriers." (PMID 27249024, 2016). "It is also important to note that the PHIs are likely to have different levels of selectivity for the PHD isoforms in cells and may, to varying extent, inhibit other members of the 2OG dioxygenase family (e.g. BIQ has been reported to inhibit the fat mass and obesity protein FTO in vitro)." (PMID 27502280, 2016). "As it is unknown for all identified SNPs outside of FTO whether or not there is a true association with both obesity and OA, there was difficulty in comparing the ABF and P‐value approaches." (PMID 26411566, 2015). "Regardless of whether the obesity-associated SNP affects FTO expression levels, these studies have clearly proven an important role of FTO in the regulation of body weight, independent of IRX3, IRX5, and RPGRIP1L." (PMID 26788058, 2015). "While it remains controversial as to whether the obesity-related SNPs in FTO act via modulation of FTO function or by influencing adjacent genes such as IRX3 and RPGRIP1L, our results provide firm evidence that FTO modulates adipogenesis, and thereby fat mass, both in vitro and in vivo." (PMID 25881961, 2015). "In addition, different nutritional perturbation lead to differential effects on FTO regulation e.g., placental expression of the obesity-associated gene FTO is reduced by fetal growth restriction but not by macrosomia in rats and humans." (PMID 26402696, 2015). "On the other hand, results from a Danish study using the polymorphisms of the FTO and MC4R genes, and from a collaborative Canadian study using the FTO gene polymorphism as instruments for obesity, suggested a possible protective effect of obesity on psychological distress and depression." (PMID 26167892, 2015). "Furthermore, rs1421025 SNP located in intron 1 of the FTO gene (as rs1558902 tested in this study) showed absence of association to obesity in Mexican children." (PMID 25890290, 2015). "Whether or not alterations in FTO expression are responsible for the obesity-associated SNPs in intron 1 of FTO remains to be unequivocally answered." (PMID 26788058, 2015). "We believe that the effect of FTO-rs9939609 on the risk of tuberculosis may not solely be attributed to its role in the risk of obesity." (PMID 25377722, 2014).
Obesity (continued). "However, the contribution of the FTO common variants to obesity is controversial in Han Chinese, some studies showed rs9939609 was statistically associated with BMI, but other results reported FTO gene is not statistically associated with obesity." (PMID 24911064, 2014). "Therefore, FTO might be involved in the incidence of obesity by both direct and indirect mechanisms." (PMID 25110886, 2014). "Thus, FTO is an important factor for the development of obesity." (PMID 25144618, 2014). "However, there have been no reports on the associations of other in FTO loci with the risk of obesity, particularly in school-age Asian children in China." (PMID 25251416, 2014). "As we known, Variants of FTO gene (such as rs9939609, rs8050136, rs1421085 and rs9930506) have been consistently reported to be associated with obesity in recent studies, but there have been no studies tested the potential role in antipsychotic-related obesity except rs9939609." (PMID 25278160, 2014). "Further analyses of African American children also could not find association of the FTO SNP with obesity." (PMID 24719615, 2014). "Interestingly, as the effect of FTO variants on T2D is only via obesity, the FTO locus was not identified in T2D GWAS using cases and controls matched for BMI." (PMID 24744783, 2014). "However, overexpression of FTO produces increased food consumption resulting in obesity." (PMID 24019958, 2013). "We also observed that high fat intake may accentuate the associating effect of the FTO genotype on fat mass and obesity, but none of our previous studies have investigated the association with specific food groups." (PMID 23589710, 2013). "Interestingly, FTO, MC4R and BDNF loci were most significantly associated with class III obesity." (PMID 23950976, 2013). "In both studies, we genotyped six SNPs that are known to be associated with risk of obesity in European populations: rs17782313 near MC4R; rs2815752 near NEGR1; rs7754561 near ENPP1; rs1805081 in exon 6 of NPC1; rs10938397 near GNPDA2 and rs1421085 in intron 1 of FTO." (PMID 23375129, 2013). "Besides, studies support that the association of FTO rs9939609 and the MC4R rs17782313 polymorphisms with type-2 diabetes and obesity could be modulated and depended on diet." (PMID 23849767, 2013). "Although we adjusted BMI for adiposity in detecting the association of FTO polymorphism with T2D risk, we cannot rule out the possibility of residual confounding of obesity, because the alternative measures (such as DEXA fat mass) of adiposity were not available in this study." (PMID 24053193, 2013). "Moreover, we also observed major age and gender differences as association of FTO variant with BMI and obesity was found in adult females only and not in girls." (PMID 24102053, 2013). "However, initial studies in European populations reported no gender differences in association of FTO common variant with obesity." (PMID 24102053, 2013). "It is also suggested that both type-2 diabetes and obesity had a common genetic etiology from the same 16.3 encoding region were FTO is located, and probably this is not the only susceptibility gene on this region which share the risk for both obesity and type-2 diabetes." (PMID 23849767, 2013). "Moreover, a few studies failed to associate some FTO polymorphisms and obesity, highlighting the need of more studies in different populations to better understand the role of FTO gene in obesity." (PMID 23342142, 2013). "Our study population presented a prevalence of obesity of ~79%, and this might explain the absence of association of FTO SNPs with T2D." (PMID 22454631, 2012). "We believe that further studies are warranted, with a greater number of subjects, to examine whether other common variants in the FTO and UCP-1 genes could be synergistic in the increased risk for obesity or obesity related phenotypes in the Brazilian and other multiethnic populations." (PMID 23134754, 2012).
Obesity (continued). "Additionally, this study is the first to identify the effects of FTO knockdown on AMPk phosphorylation, and we suggest that AMPk may be a primary mediator of FTO’s influence on energy intake and obesity." (PMID 22675562, 2012). "For example, the FTO gene encodes for an enzyme that is able to remove methyl groups from DNA, long-term exposure to high-fat diet can decrease the melanocortin-4 receptor (MC4R) gene methylation and high-fat diet–induced obesity can modify leptin methylation patterns." (PMID 24392269, 2012). "Despite lack of FTO genotype-aerobic fitness interaction, the genotype AA carriers are more susceptible to obesity and may benefit from increased aerobic fitness to a greater extent due to its favourable effects on the regulation of body weight." (PMID 23284729, 2012). "While many individual studies have suggested that physical activity (PA) may attenuate the effect of FTO on obesity risk, other studies have not been able to confirm this interaction." (PMID 22069379, 2011). "Thus, FTO may contribute to the programming of obesity through both central and peripheral mechanisms." (PMID 21980407, 2011). "However FTO has only shown to play a role in obesity and we controlled for BMI." (PMID 21489227, 2011). "However, heterozygous loss-of-function mutations in FTO are found in both lean and obese subjects and do not contribute to monogenic obesity." (PMID 22043165, 2011). "Similarly the odds ratios for the respective obesity risk effect alleles did not vary strongly by group (children and adolescents vs. adults) with point estimates ranging between 1.35–1.45 (FTO), 1.35–1.45 (TMEM18) and 1.10–1.19 (SDCCAG8)." (PMID 20421936, 2010). "Exploration of associations between genotypes and metabolic/obesity related variables in patients with PCOS revealed some evidence for an association of variants in FTO and TCF7L2, whereas no indication of association was observable for SNPs in INSIG2 and MC4R." (PMID 20092643, 2010). "However, evidence up-to-date suggests that the FTO variant confers a predisposition to obesity to be involved in the regulation of food intake rather than in the regulation of energy expenditure." (PMID 20098739, 2010). "Moreover, patients carrying homozygous loss-of-function mutations in FTO show severe growth retardation and multiple malformations, but no record of obesity." (PMID 21103374, 2010). "Thus, the molecular structure of the TMEM18 protein is very uncommon in terms of other proteins in the human genome and surely very much different compared to other proteins involved in obesity, such as the enzyme FTO and the G protein-coupled melanocortin receptor, MC4R." (PMID 20380707, 2010). "In addition, further understanding of the linkage disequilibrium pattern of the FTO gene in different populations may aid in the search of casual gene for obesity." (PMID 20598163, 2010). "We could not find any association between FTO variant and obesity or obesity measurements at any of the ages studied." (PMID 20003232, 2009). "For example, genotype‐guided diets use genetic variations, such as FTO and TCF7L2, with obesity and glucose metabolism to personalize carbohydrate intake and improve diabetes management." (PMID 41019177, 2025). "Conversely, our study found a positive correlation between FTO and MEG3 expression in PBMCs from children with obesity." (PMID 40806129, 2025). "Across diverse ancestries, FTO and MC4R consistently emerge as the most replicated obesity loci, demonstrating cross-population robustness." (PMID 41302083, 2025). "GWAS of SevO found numerous susceptibility loci that intersected with earlier-identified BMI loci including the archetypal FTO, MC4R, SH2B1 and NPC1 suggesting little etiological heterogeneity between obesity subgroups." (PMID 40939575, 2025).
Obesity (continued). "Enrichment of A. muciniphila leads to generate more ILA to facilitate cholesterol converts to CA in FTO/m6A/CYP8B1 coordinated manner, thereby reversing obesity‐related phenotypes via activating FXR in adipose tissue." (PMID 39888270, 2025). "Our findings indicate that the expression of MEG3, FTO, and ATF4 is altered in children with obesity." (PMID 40806129, 2025). "The objective of the present study was to describe possible interactions of leptin, adiponectin, FTO rs9939609, and TMEM18 rs6548238 in children and adolescents with asthma, under the influence of obesity." (PMID 39159917, 2025). "In conclusion, this study demonstrates altered expression of FTO and MC4R in the gastric tissue of patients with clinical obesity and suggests links with adipokine regulation and insulin resistance." (PMID 41423640, 2025). "Long non-coding RNAs, particularly MEG3, are involved in obesity through regulation of lipogenic genes including ATF4, FTO, SREBP1, FASN, and ACACA." (PMID 40806129, 2025). "Thus, the role of FTO in amino acid sensing may provide some clues toward understanding the cellular basis of this physiological phenomenon and reveal new therapeutic targets in the battle against the growing prevalence of obesity and asthma." (PMID 39159917, 2025). "For example, many loci near genes (FTO, ADCY3, and BDNF) are polygenic and related to obesity and other metabolic diseases." (PMID 40024983, 2025). "The mRNA expression of SREBP1 (p = 0.0176), FASN (p = 0.0412), ACACA (p = 0.0255), FTO (p < 0.0001), and ATF4 (p < 0.0001) was significantly reduced in the obesity group compared to the control group." (PMID 40806129, 2025). "We observed significant upregulation of FTO and downregulation of MC4R in the gastric tissue of patients with obesity, correlating with altered adiponectin levels and insulin resistance." (PMID 41423640, 2025). "We calculated the Hardy-Weinberg Equilibrium (HWE) for six genes (CLOCK, GHRL, FTO, LEP, LEPR, MC4R) related to obesity, using genotype frequencies from our dataset." (PMID 39203789, 2024). "FTO controls RUNX1T1 splicing by regulating m6a and thus FTO directly modulates obesity at the m6A level." (PMID 39458556, 2024). "By focusing on healthy individuals, the study sought to determine whether reduced maximal fat oxidation linked to the FTO rs9939609 polymorphism contributes to genetic susceptibility to body fat accumulation, even in individuals who have not yet developed obesity or related comorbidities." (PMID 39858551, 2024). "This study investigates the relationship between six obesity-related genes (CLOCK, FTO, GHRL, LEP, LEPR, MC4R) and their impact on BMI, WC, HC, WHR, and emotional eating behavior in 220 Romanian adults." (PMID 39203789, 2024). "The FTO rs9939609 SNP was previously incorporated in GRS models predicting BMI and obesity across diverse populations, including African American and Caucasian populations, European adolescents, and the Iranian population." (PMID 38732542, 2024). "Previous GWASs have demonstrated the association of the studied polymorphic loci ADCY3 rs1167627272, CLOCK rs1801260, FTO rs1421085, GPR61 rs41279738, RP11-775H9.2 rs1296328, SLC22A3 rs9364554, and TFAP2B rs734597 with obesity-related phenotypes." (PMID 39766774, 2024). "BDNF, BDNF-AS, and FTO were overrepresented in the BMI gene set (PFDR = 3.80 × 10−6, FDR meant false discovery rate) and obesity gene set (PFDR = 2.69 × 10−5)." (PMID 38461358, 2024). "Recently it was found that FTO can influence IRX3 expression, a protein involved in obesity and the browning of adipose cells resulting that carriers of protective FTO T allele has lower IRX3 expression and lower adipose tissues than AA homozygotes." (PMID 39203789, 2024). "FTO upregulates RPGRIR1L in humans, increasing the lean body mass; furthermore, Iroquois Homeobox 3 (IRX3) which was also upregulated by FTO in human obesity, was found on the same loci in bats." (PMID 39596561, 2024).
Obesity (continued). "The less affected by obesity were CLOCK/TT genotype, average weight, 69.33 kg, BMI 24.07, WC 76.37 cm, HC 97.91 cm, WHR of 0.78 and FTO/TT, average weight 66.58 kg, BMI 23.32, WC 73.99 cm, HC 96.89 cm, WHR 0.76." (PMID 39203789, 2024). "We integrate multi-omics and functional information to resolve the colocalizing signals and identify high-confidence effector genes, including FTO and IRX3, which provide proof-of-concept insights into the epidemiologic link between obesity and both diseases." (PMID 37433298, 2023). "Large-scale genome-wide association studies have shown that genetic variations in BMI-related genes, such as FTO, BDNF, and MC4R, are closely related to obesity." (PMID 37683016, 2023). "Hence, despite a great deal of data implicating FTO as the gene involved in obesity, in fact through refined methodologies (similar to what we propose here) in the absence of eQTL support, other genes that are physically located near FTO are actually the physiologically relevant effector genes." (PMID 36608130, 2023). "Highly infrequent single gene mutations (such as LEP, LEPR and POMC) stand for rare cases of monogenic obesity; however, some of them are also related to polygenic obesity (such as MC4R and FTO)." (PMID 36980866, 2023). "Further well-designed studies are required in different racial populations to elucidate the biology of FTO SNPs and their impacts on the relation of DII to obesity phenotypes." (PMID 38618529, 2023). "Our findings suggest that C alleles at FTO rs1421085 suppress the thermogenic activation of human abdominal SC adipocytes; even long-term rosiglitazone treatment could not compensate for the effect of the obesity-risk genotype." (PMID 37416800, 2023). "The FTO and the MC4R are typical representatives of obesity, and more evidence supports the relationships between the two loci and stroke events." (PMID 36530622, 2022). "Baicalin has been reported to ameliorate high-fat diet-induced obesity and hepatic steatosis through carnitine palmitoyltransferase 1 (CPT1), of which mRNA serves as a potential substrate of FTO for m6A modification, predicted by m6A-Atlas." (PMID 35769384, 2022). "In a diet-induced obesity mouse model treatment with entacapone, FOXO1, as a direct substrate of FTO, can induce intrahepatic gluconeogenesis and adipose tissue thermogenesis, resulting in weight loss and a decrease in the fasting blood glucose concentration." (PMID 35682599, 2022). "Our findings collectively suggest the anti-obesity potential of SMF and SAF via the downregulation of the FTO gene." (PMID 35800074, 2022). "For the genes NRF1, FTO, and LEPR, our study demonstrates a race-specific difference in the DNA methylation of these obesity-related genes." (PMID 36360268, 2022). "Hence, it had been speculated that the FTO gene polymorphism might play important roles in the risk of immune-related human infectious diseases such as PTB, and the roles on PTB occurs through obesity-related immunocompetence." (PMID 36619747, 2022). "DHA promotes mitochondrial biogenesis and skeletal muscle fiber remodeling via FTO/m6A/DDIT4/PGC1α signaling, protecting against obesity-induced decline in skeletal muscle function." (PMID 35135551, 2022). "For each participant, three SNPs in three genes (FTO rs9939609, TFAP2B rs987237, PLIN1 rs894160) related to obesity were genotyped." (PMID 36142109, 2022). "The m6A demethylase FTO may regulate adipocyte differentiation and adipogenesis by regulating the expression of proteins such as gastric starvation hormone, pro-adipogenic factors and peroxisome proliferator-activated receptor, thereby affecting the development of obesity." (PMID 36733447, 2022). "Following the determination of the FTO crystal structure by Chai's group in 2010, FTO is widely viewed as an attractive biological target; potentially a small-molecule inhibitor specifically targeting FTO could be developed for the treatment of metabolic disorders such as obesity and diabetes." (PMID 35769384, 2022).